NLRP3 (NLR family pyrin domain containing 3)
Diseases named in the same sentence as NLRP3 in open-access papers (continued):
Sharing a sentence is not in itself a finding about the gene and the disease.
triple-negative breast carcinoma (19 papers, 2019 to 2026). An invasive breast carcinoma which is negative for expression of estrogen receptor (ER), progesterone receptor (PR), and human epidermal growth factor receptor 2 (HER2). "The in vitro and in vivo results demonstrated that IC@PCH NP-mediated photothermal-chemotherapy treatment led to pyroptosis via the NLRP3/caspase-1 classical pathway, which had a significant therapeutic effect on triple-negative breast cancer." (PMID 40376201, 2025). "MiRNA-1290 suppressed RT-induced pyroptosis and decreased the radiosensitivity of triple-negative breast cancer cells by targeting NLRP3." (PMID 39398428, 2024). "Considering the impact of inflammatory processes in cancer progression, there is a strong concern to develop therapeutic strategy targeting NLRP3 inflammasome for triple-negative breast cancer (TNBC) treatment." (PMID 39433537, 2024). "Meanwhile, NLRP3 was reported to enhance gemcitabine-based resistance in triple-negative breast cancer cells." (PMID 37304662, 2023). "Recently published studies have shown that Cisplatin induces scorch death through activating the MEG3/NLRP3/caspase-1/GSDMD pathway in triple-negative breast cancer." (PMID 35938142, 2022). "Suppressing the activation of the NLRP3 inflammasome can also prevent the outgrowth and spontaneous metastasis of triple-negative breast cancer cells." (PMID 34457117, 2021). "The side effects associated with the chemotherapy of triple-negative breast cancer (TNBC), such as nucleotide-binding oligomerization domain (NOD)-like receptor family (NLR), pyrin domain containing 3 (NLRP3) inflammasome activity, are responsible for the treatment failure and high mortality rates." (PMID 39940603, 2025). "The findings indicated that miRNA-1290 might impair the radiosensitivity of triple-negative breast cancer cells by inhibiting NLRP3-mediated pyroptosis, which might be regarded as a novel therapeutic option." (PMID 39398428, 2024). "Therefore, we then focused on the effect of BBR on the release of inflammatory cytokines and the expression of proteins and mRNAs in the NLRP3 Inflammasome signaling pathways in triple-negative breast cancer cell line MDA-MB-231." (PMID 31412862, 2019). "In triple-negative breast cancer, cisplatin activated MEG3/NLRP3/CASP-1 pathway to induce cell pyroptosis, which suggested that MEG3 was involved in the pyroptosis pathway of cisplatin therapy." (PMID 36281290, 2022). "By using in vivo and in vitro brain metastasis models, as well as human samples to study the role of the NLRP3 inflammasome in triple-negative breast cancer (TNBC) brain metastases, we found NLRP3 inflammasome components and IL-1β to be highly and specifically expressed in peritumoral astrocytes." (PMID 37749707, 2023). "Furthermore, a reduction of NLRP3 and PYCARD expression has been observed in triple negative breast cancers (TNBCs) with respect to the Luminal phenotypes (p = 0.017 and p = 0.0015, respectively)." (PMID 35745570, 2022).
bladder cancer (18 papers, 2020 to 2025). "In another study, there was a relationship between NLRP3 rs10754558 and the risk of bladder cancer development, lymph node metastasis, the tumor size, mainly in alcohol drinkers and smokers." (PMID 38915451, 2024). "Homogeneous Polyporus polysaccharide resets tumor-associated macrophages through NF-κB/NLRP3 signaling to inhibit bladder cancer." (PMID 39201564, 2024). "miRNAs are critical regulators of NLRP3 inflammasome activity, and assessing the expression levels of inflammasome-related genes and their regulatory miRNAs may provide a promising diagnostic tool for bladder cancer." (PMID 40718836, 2025). "This review focuses on summarizing the structure and activation mechanisms of the NLRP3 inflammasome and elucidates its role in urogenital system tumors, such as prostate and bladder cancers, highlighting its potential as a therapeutic target." (PMID 40718836, 2025). "In recent years, studies have also indicated that the NLRP3 inflammasome plays a dual role in the progression of urogenital tumors, particularly in prostate and bladder cancers." (PMID 40718836, 2025). "The NLRP3 inflammasome, along with IL-18 and IL-1β, plays a significant role in promoting the development of bladder cancer (BC) and renal cell carcinoma (RCC)." (PMID 40718836, 2025). "The potential role of inflammasomes in the early development of bladder cancer was suggested by the up-regulation of NLRP3." (PMID 39201564, 2024). "Previous studies have reported that oxidative stress and the NLRP3 and NF-κB signaling pathways are important for the maintenance of bladder epithelial cell homeostasis both in animals and in vitro models of bladder cancer and interstitial cystitis." (PMID 39071900, 2024). "High expression of the NLRP3 inflammasome is also detected in bladder cancer, making it a possible biomarker for its identification." (PMID 37715239, 2023). "However, the NLRP3 inflammasome is essential for antitumor adaptive immunity in bladder cancer (BC) and renal cell carcinoma (RCC), and its pyroptosis pathway has demonstrated potent antitumor effects." (PMID 40718836, 2025). "We further examined whether HPP could regulate macrophage polarization in the microenvironment of bladder cancer and thereby exert anticancer effects through the NF-κB and NLRP3 pathways." (PMID 32850623, 2020). "Therefore, targeting HIF-1α or NLRP3 inflammasome components may represent a novel therapeutic strategy for bladder cancer treatment." (PMID 37715239, 2023). "In addition, HPP was recognized by Toll-like receptor 2 (TLR2) and activated the signaling pathways of NF-κB and NLRP3 in a bladder cancer microenvironment model, indicating that HPP could enhance host immune system function." (PMID 32850623, 2020). "Research has shown that the expression of various NLRP genes (e.g., NLRP3, NLRP4, NLRP9) and miRNAs targeting these genes varies in urinary sediment from bladder cancer patients compared to healthy controls." (PMID 40718836, 2025). "However, NLRP3, NLRP4, and NLRP9 were significantly increased in the urine and tumor tissue samples of patients with bladder cancer compared with those in healthy people." (PMID 34869390, 2021). "The results illustrated that HPP has good therapeutic effects on bladder tumors and drives TAM polarization to improve the tumor inflammatory microenvironment via NF-κB/NLRP3 signaling pathway, which suggested that HPP might be a potential therapeutic agent for bladder cancer." (PMID 37836659, 2023).
dengue (18 papers, 2015 to 2025). "In that study, flow cytometric analysis of intracellular NLRP3 confirmed that NLRP3 protein was present in platelets from both dengue‐infectious patients and healthy controls." (PMID 36852778, 2023). "Around the same time, it was shown that Dengue-induced NLRP3 inflammasome activation increased platelet-mediated endothelium permeability and this was followed by increased expression of IL-1β in vitro and in patient serum." (PMID 36298668, 2022). "Then they showed the IL-1β production induced by E III was mediated by NLRP3 and caspase-1 and suggested this was responsible for Dengue-induced pathogenesis." (PMID 36298668, 2022). "Our group has previously demonstrated that platelet activation in dengue induces NLRP3 inflammasome activation and increased IL-1β secretion, which contributes to increased endothelial permeability." (PMID 36569864, 2022). "Platelets mediate the increase in endothelium permeability in dengue through NLRP3 inflammasome activation." (PMID 33728029, 2021). "In this study, we investigated the activation of the NLRP3 inflammasome in endothelial cells (HMEC-1) following dengue virus infection." (PMID 32210961, 2020). "Spleen Tyrosine Kinase (Syk) augments IL-1β induction during antibody-enhanced dengue virus infection in primary human monocytes, however caspase-1 and NLRP3 are required for the maturation of pro-IL-1β during antibody-dependent enhancement." (PMID 32210961, 2020). "In summary, our observations provide insight into the dengue-induced inflammatory response mechanism and highlight the importance of DENV-2 NS2A and NS2B proteins in activation of the NLRP3 inflammasome during dengue virus infection." (PMID 32210961, 2020). "DENV infection activate the NLRP3 inflammasome, and subsequent activation of caspase-1, and caspase-1 dependent secretion of IL-1β in platelets microparticles from patients with dengue as well as when platelets get exposed to DENV in vitro." (PMID 33014899, 2020). "We demonstrated that dengue induces NLRP3-inflammasome assembly and caspase-1-dependent IL-1β secretion in platelets." (PMID 25814789, 2015). "Apart from the antiviral property, mefenamic acid also showed promise in dengue treatment by targeting the NLRP3 inflammasome, a key driver of inflammation and vascular leakage in severe dengue cases like dengue hemorrhagic fever (DHF) and dengue shock syndrome (DSS)." (PMID 40851698, 2025). "The M protein of Dengue was unable to induce vascular damage in NLRP3 knockout mice." (PMID 36298668, 2022). "We have previously shown that during dengue there is a significant positive correlation between thrombocytopenia and IL-1β release and that dengue infection leads to assembly of NLRP3 inflammasomes, activation of caspase 1, and caspase 1–dependent IL-1β secretion in dengue." (PMID 36189282, 2022). "Similarly, NLRP3 activation in platelets was attributed to excessive reactive oxygen species (ROS) production by mitochondria upon dengue virus infection." (PMID 34360659, 2021). "Indeed, in dengue mouse models, anti-NS1-Abs activated NLRP-3 by binding to FcγRIIIs resulting in severe disease." (PMID 33194836, 2020). "Although an increase in neutrophils is not observed in dengue, NLRP3 activation in many types of cells has been observed with an increase in NET components in the serum of patients with DHF, suggesting that activation of neutrophils is likely to play a role in severe dengue." (PMID 35786403, 2022). "Although a recent study on macrophages and platelets have shown the importance of the Syk-coupled C-type lectin CLEC5A and RIP kinases during DENV-2-induced NLRP3 inflammasome activation, no direct role of dengue proteins in the activation of inflammasomes have been reported." (PMID 32210961, 2020).
hyperhomocysteinemia (18 papers, 2015 to 2026). A serious metabolic condition caused by mutations in the MTHFR gene, medications, or nutritional deficiency. "The underlying mechanism for hyperhomocysteinemia-induced NLRP3 inflammasome activation is through the generation of ROS." (PMID 37074484, 2023). "In this regard, endothelial NLRP3 inflammasome was found to be activated upon different proatherogenic stimuli such as cholesterol crystals, ATP, uric acid, hyperhomocysteinemia, and damage-associated molecular patterns via different pathways." (PMID 36252682, 2022). "Moreover, hyperhomocysteinemia induces inflammation by activating NLRP3 inflammasome in ApoE-deficient mice." (PMID 37074484, 2023). "In a model concerning hyperhomocysteinemia-induced renal harm, the activation of NLRP3 inflammasome, which was instigated by NADPH oxidase-driven redox signaling, led to the recruitment of immune cell infiltration." (PMID 40692778, 2025). "Previous study on hyperhomocysteinemia kidney damage revealed that NLRP3, ASC, caspase-1 all expressed in mice sertoli cell, and homocysteine activated the NLRP3 inflammasome, followed by cytoskeleton rearrangement." (PMID 27721494, 2016). "Hyperhomocysteinemia may worsen PD neuropathology and related neuroinflammation by activating the NF-B and NLRP3 inflammasome signaling pathways." (PMID 37074484, 2023). "Thus, hyperhomocysteinemia-induced NLRP3 inflammasome activation is mainly through ROS generation, cholesterol biosynthesis, and generation of oxLDL." (PMID 37074484, 2023). "Taken together, hyperhomocysteinemia through activation of NF-κB and NLRP3 inflammasome signaling pathways may augment PD neuropathology and associated neuroinflammation." (PMID 37074484, 2023). "Activation of NLRP3 inflammasome has been shown to be involved in podocyte injury and glomerular sclerosis in hyperhomocysteinemia, and inhibition of NADPH oxidase or knockdown of ASC or caspase-1 inhibition may play a protective effect." (PMID 32175320, 2020). "Therefore, hyperhomocysteinemia may directly affect PD neuropathology or indirectly through activation of NLRP3 inflammasome." (PMID 37074484, 2023). "In a model of hyperhomocysteinemia-induced renal injury, NADPH oxidase-mediated redox signaling was responsible for switching on NLRP3 inflammasome activation, which recruited immune cell infiltration, ultimately leading to glomerular injury and sclerosis." (PMID 37876929, 2023).
spinal cord injury (18 papers, 2016 to 2026). Penetrating and non-penetrating injuries to the spinal cord resulting from traumatic external forces (e.g., WOUNDS, GUNSHOT; WHIPLASH INJURIES; etc.). "The NADPH oxidase inhibitor apocynin suppresses AOPP-induced microglial pyroptosis via the ROS-dependent MAPK-NF-κB signaling pathway and NLRP3-GSDMD pathway following spinal cord injury (SCI), thereby improving SCI prognosis." (PMID 40918101, 2025). "NLRP3 inflammasome is also recognized to have an important role in the spinal cord tissue after traumatic spinal cord injury (SCI), and targeting the NLRP3 inflammasome can inhibit neuroinflammation, thereby improving functional recovery in SCI rats." (PMID 27672241, 2016). "This study aimed to evaluate the expression of cytosine monophosphate kinase 2 (CMPK2) and activation of the NLRP3 inflammasome in rats with spinal cord injury (SCI) and to characterize the effects of electroacupuncture on CMPK2-associated regulation of the NLRP3 inflammasome." (PMID 35401582, 2022).
cystitis (17 papers, 2015 to 2025). Inflammation of the urinary bladder. "Various reports have established a crucial role for the NLRP3 inflammasome in acute and chronic cystitis caused by uropathogenic E. coli (UPEC)." (PMID 38392844, 2024). "Our study provides a better understanding ofn the underlying mechanisms of ketamine in ER stress and TXNIP/NLRP3 in vivo and in vitro as well as target strategy for treating ketamine-associated cystitis." (PMID 31652453, 2019). "In recent years, it was found that NLRP3 inflammation was involved in the progression of cystitis, therefore, targeting the TXNIP/NLRP3 signal axis may be an effective therapeutic target for treating ketamine-associated cystitis." (PMID 31652453, 2019). "Hispidulin also can suppress the expressions of PTGS2 and NLRP3 inflammasome to improve cyclophosphamide-induced cystitis." (PMID 41340657, 2025). "NLRP3-pyroptosis is an effective defense against acute cystitis as it mediates the exfoliation of bladder epithelium and the subsequent elimination of adherent and intracellular UPEC." (PMID 38392844, 2024). "Intrathecal injection of miR‐9‐enreched MSCs derived exosomes were effective in the treatment of cystitis‐induced pelvic/bladder nociception by inhibiting TLR4/NF‐κb/NLRP3 signal pathway in central nervous system of IC/BPS mice." (PMID 38415918, 2024). "The importance of NLRP3 in mechanisms of CYP-induced cystitis was demonstrated in previous studies showing that inhibition of NLRP3 prevented increase in urinary IL-1β levels and reduced inflammation and bladder dysfunction in CYP-treated rats." (PMID 35563427, 2022). "In CYP-induced cystitis, activation of the NLRP3 inflammasome would occur in response to urothelial cell damage caused by acrolein, a CYP metabolite that is viewed as being responsible for the effects of CYP in the bladder." (PMID 35563427, 2022). "Inhibiting the synthesis of COX-2 or NLRP-3 can protect mice from cystitis induced by uropathogens, but except GBS-induced cystitis, because GBS colonized more in NLRP-3-deficient mice compared with wild type mice." (PMID 36081496, 2022). "The present study is in line with the proposed NLRP3 involvement in CYP-induced cystitis and suggests that the observed anti-inflammatory effect of PMF90 can be associated with the modulation of NLRP3 activity." (PMID 35563427, 2022). "In this study, we found that NLRP3 levels significantly increased in bladder macrophages in diabetic mice that underwent cystitis." (PMID 36405726, 2022). "Together, these data suggest that specific depletion of NLRP3 in macrophages alleviates the severity of cystitis in diabetic mice." (PMID 36405726, 2022). "To summarize, our data suggest that macrophage-depletion of NLRP3 attenuates the severity of cystitis in a diabetic status." (PMID 36405726, 2022). "Secreted IL-1β is a strong signature cytokine for NLRP3 inflammasome activation by cytosolic LPS sensing, with a critical role for the development of acute cystitis." (PMID 33102527, 2020). "In conclusion, we revealed that in rat and cells models, ketamine-associated cystitis was associated with ER stress, apoptosis, TXNIP/NLRP3 aix and ROS." (PMID 31652453, 2019). "Asc and Nlrp3 were defined as key resistance determinants and IL-1β activation as a crucial step in the pathogenesis of acute cystitis." (PMID 27732661, 2016). "Infected Asc-/- and Nlrp3-/- mice developed severe, acute cystitis with enlarged bladders, edema and hyperemia compared to uninfected bladders." (PMID 27732661, 2016). "Taken together, these data implicate hemolysin and the NLRP3 inflammasome in the priming response to enhanced chronic cystitis." (PMID 25569799, 2015). "Building on this foundation, we innovatively established a cystitis model by injecting LPS into the bladders of rats, aiming to explore in detail the underlying mechanism by which KZMK effectively inhibits the triggering of the NLRP3 inflammasome." (PMID 40004227, 2025).